PIK3CA (phosphatidylinositol-4,5-bisphosphate 3-kinase catalytic subunit alpha)
Diseases named in the same sentence as PIK3CA in open-access papers (continued):
Sharing a sentence is not in itself a finding about the gene and the disease.
colorectal cancer (continued). "Half of the activating mutations in PIK3CA occurring in colorectal cancers concern hotspots of amino acid positions E545, E542 and Q546 of the helical domain or position H1047 of the kinase domain, while the other half is distributed across the gene." (PMID 36079062, 2022). "Previous studies have shown that about 15%-20% of patients with colorectal cancer carry PIK3CA activation mutations, and patients with PI3KCA mutations have better OS and progression-free survival (PFS)." (PMID 35707003, 2022). "In contrast, PIK3CA mutations are encountered in colorectal cancers with either KRAS or BRAF mutations with an equal or higher prevalence than in cancers with wild type KRAS and BRAF." (PMID 36295658, 2022). "Mutation-induced overexpression of the PIK3CA and Akt genes in colorectal cancer promotes the activation of PI3K/Akt pathways, and enhances the proliferation and survival of cancer cells while withstanding apoptosis." (PMID 36139789, 2022). "Previous studies in colorectal cancer showed that PIK3CA mutations reprogram glutamine metabolism by upregulating GPT2 in colorectal cancer cells, making these cancer cells more dependent on glutamine for their survival." (PMID 36010673, 2022). "Mutations in PIK3CA are the most frequent mutations in the receptor tyrosine kinase-initiated pathways in colorectal cancers with BRAF mutations, as the even more frequent KRAS mutations are mutually exclusive with BRAF mutations." (PMID 36295658, 2022). "PIK3CA-activating mutations have also been studied in colorectal cancer (CRC), where they are commonly identified in 20% of patients." (PMID 35158773, 2022). "Consistent with the high prevalence of MSI and POLE subtype, BRAF/PIK3CA double mutant colorectal cancers in TCGA had a high Tumor Mutation Burden (TMB) above 200 in 86.4% of cases." (PMID 36079062, 2022). "In colorectal cancer, PIK3CA is mutated in 20% to 25% of cases and is the second most commonly mutated oncogene after KRAS." (PMID 36295658, 2022). "For instance, aspirin use was associated with reduced rate of colorectal cancer recurrence in patients with PIK3CA-mutant tumors compared with patients with PIK3CA wild-type tumors." (PMID 36545311, 2022). "A similar association of hotspot PIK3CA mutations with a high tumor mutation burden has been described in colorectal cancers." (PMID 35329928, 2022). "BRAF and PIK3CA are oncogenic kinases commonly mutated in colorectal cancers and can be targeted through small molecule kinase inhibitors." (PMID 36079062, 2022). "Increasing evidence has revealed the presence of common mutations of PIK3CA in various types of cancer, such as gastric cancer, ovarian cancer, colorectal cancer, and lung cancer." (PMID 34367282, 2021). "PIK3CA mutations have been found to increase glutamate pyruvate transaminase 2 (GPT2) in colorectal cancer (CRC) cells." (PMID 34200820, 2021). "Colorectal cancer patients with the PIK3CA mutation have been reported to respond poorly to primary chemotherapy than those without the PIK3CA mutation." (PMID 33237662, 2021). "Hotspot mutations of PIK3CA were found in a broad scope of cancers, including melanoma, breast cancers, colorectal cancers, gastric cancers, liver cancers, etc., and most of these mutations have been confirmed to promote an oncogenic gain-of-function effect." (PMID 33827485, 2021). "In a single-center retrospective study, we obtained KRAS and PIK3CA mutational status in a cohort of 153 patients with a first diagnosis of colorectal cancer receiving tumor surgery with curative intent." (PMID 34638442, 2021). "In early diagnosis of patients with colorectal cancer, mRNA analyses associated with mutation analyses are needed to precisely identify the PIK3CA effect." (PMID 33237662, 2021).
colorectal cancer (continued). "This is especially critical, as some clinical trials recruit colorectal cancer patients into aspirin trials only in case the tumors harbor PIK3CA mutations (see: clinicaltrials.gov, NCT02467582)." (PMID 34638442, 2021). "PIK3CA mutations have been reported in about 80% of mutations in 10%–20% of colorectal cancers, exon 9 and exon 20 at two hot spots." (PMID 33237662, 2021). "While patients whose tumours did not carry a PIK3CA mutation had no observed benefit from aspirin therapy in these trials, patients whose tumours carry PIK3CA mutations had a HR of 0.11–0.18 for colorectal cancer-specific death." (PMID 34544470, 2021). "Actionable variants of oncogenes, such as KRAS and PIK3CA, are frequently determined in both ERONs and colorectal cancers." (PMID 33557369, 2021). "First line chemotherapy response and PIK3CA mutation correlation were evaluated and evaluated in 440 colorectal cancer patients in medical records." (PMID 33237662, 2021). "Phosphoinositol-3-kinase, catalytic α-peptide (PIK3CA) gene mutation is one of the most common mutations in human cancer and a known biomarker of breast cancer, colorectal cancer, cervical cancer, endometrial cancer, ovarian cancer and other cancer types." (PMID 34976987, 2021). "A total of 34% of the patients with wild-type PIK3CA tumors and 33% of the patients with a tumor mutation in the PIK3CA gene took aspirin regularly after the diagnosis of colorectal cancer." (PMID 34638442, 2021). "The frequency of PIK3CA gene mutation in colorectal cancer patients has been found to be 9.55%, and this has been reported to be associated with late TNM staging and low histological grade." (PMID 33237662, 2021). "We found that patients with regular aspirin use after the diagnosis of colorectal cancer and combined wild-type PIK3CA and mutated-KRAS tumors showed a significant survival benefit." (PMID 34638442, 2021). "In a retrospective study, we obtained KRAS and PIK3CA mutational status in a cohort of 153 patients with a first diagnosis of colorectal cancer receiving tumor surgery with curative intent." (PMID 34638442, 2021). "Although aspirin is primarily used as an antipyretic and analgesic drug, many studies have shown that aspirin can effectively prolong the survival of colorectal cancer patients with PIK3CA mutations." (PMID 32000660, 2020). "These genetic alternations are relevant as both APC and PIK3CA mutations are commonly present in human colorectal cancers." (PMID 32170841, 2020). "This indicates that the PI3K/Akt/Raptor pathway is abnormally activated in colorectal cancer with PIK3CA mutation." (PMID 32000660, 2020). "Phosphatidylinositol 3-kinase, catalytic subunit alpha (PIK3CA) is an oncogene mutated in 10% to 25% of colorectal cancers (CRCs)." (PMID 32365913, 2020). "In this study, immunohistochemistry was used to detect the expression levels of PI3K and Raptor in colorectal cancer patients with PIK3CA mutation and PIK3CA wild-type patients." (PMID 32000660, 2020). "ATM and PIK3CA mutations were present in a quarter of the patients, again a frequency expected for colorectal cancer." (PMID 32784964, 2020). "When it comes to patients who have already developed colorectal cancer, data concerning clinical usefulness of NSAIDs are rarer; use of aspirin seems to improve survival particularly in patients with colorectal cancer harbouring PIK3CA mutations." (PMID 32977434, 2020).
colorectal cancer (continued). "While some driver mutations are targetable, others have shown to confer resistance to standard therapy choices such as KRAS, BRAF, and PIK3CA mutations in colorectal cancer." (PMID 32760731, 2020). "Phosphatidylinositol 3-kinase, catalytic subunit alpha (PIK3CA) is an oncogene often mutated in colorectal cancer (CRC)." (PMID 32365913, 2020). "Our previous study in colorectal cancer also demonstrated a higher incidence of mutations in PI3K/AKT pathway genes (PIK3CA, PTEN, and AKT1) in the EMAST+/MSI-H tumors than in other subtypes." (PMID 32120855, 2020). "It has also been shown that PI3K/Akt/mTOR inhibitor treatments have minimal activity against advanced colorectal cancer with PIK3CA-mutations including E545K, M1043V and H1047R and that concomitant KRAS mutations frequently contribute to this resistance." (PMID 31769426, 2019). "KRAS, BRAF and PIK3CA were also presented as screen factors in colorectal cancers using their mutations." (PMID 31263147, 2019). "As a classical mitochondrial pathway, our previous study showed that the mutation in PI3K (PIK3CA) plays a vital role in several diseases, especially in colorectal cancers." (PMID 30651404, 2019). "Proliferation and survival related signaling pathways such as PI3K/AKT/mTOR and RAS/RAF/MEK/ERK play important roles in pathogeneses of solid tumors, and KRAS, BRAF, and PIK3CA (PI3K) mutations are the most common in colorectal cancer." (PMID 31624493, 2019). "We recently found that PIK3CA mutations render colorectal cancer (CRC) cells dependent on glutamine." (PMID 31844152, 2019). "We explored the association of clinico-pathological variables related to the mutational status of KRAS, NRAS, BRAF, and PIK3CA, genes that are involved in the main pathways of different solid tumors including colorectal cancer." (PMID 31036005, 2019). "Confirmed partial responses (PR) were observed in one head and neck squamous cell cancer patient and one colorectal cancer patient with PIK3CA and KRAS mutations, which indicated preliminary anti-tumor activity of GDC-0980 in combination with capecitabine." (PMID 30782187, 2019). "PIK3CA mutations (exon 9 and exon 20) and upregulation of Akt phosphorylation are associated with significantly decreased survival for colorectal cancer patients undergoing chemotherapy." (PMID 31769426, 2019). "In the present study, we demonstrated that PIK3CA mutation contributes to MEK inhibitor primary resistance and that Akt is activated in response to MEK inhibitor treatment in the PIK3CA-mutated colorectal cancer cell lines DLD-1 and HT-29." (PMID 31769426, 2019). "There are some evidence that PIK3CA mutations associated with activation of KRAS- BRAF mutation occurring in colorectal cancers." (PMID 30774815, 2018). "Very interestingly, Cohen and coworkers recently reported a high frequency of PIK3CA mutations in a subset of colorectal cancer patients defined as double somatic mismatch repair mutations." (PMID 29652830, 2018). "Mutations in KRAS exon 2, BRAF and PIK3CA are commonly present in colorectal cancer (CRC) worldwide, but few data about RAS mutations outside KRAS exon 2 are available for Chinese CRCs." (PMID 29666387, 2018). "In this study, we provided a rationale for combined treatment with IDF-11774 and an ATP6V0C inhibitor for patients with colorectal cancer that harbor PIK3CA mutations and thus, exhibit low Bcl-2 expression." (PMID 30420612, 2018). "Conversely, in the colorectal-cancer samples the PIK3CA activating mutation was more frequently associated low mTOR activity." (PMID 29137436, 2017).
colorectal cancer (continued). "We conducted this study to provide in vitro experimental evidence supporting the recent molecular pathological epidemiology studies that suggest tumor PIK3CA mutation status as a biomarker to predict benefits from aspirin therapy for colorectal cancer." (PMID 29152088, 2017). "Activating mutations in PIK3CA are present in many cancer types, including colorectal cancer, with a 10–30% mutation rate." (PMID 29069792, 2017). "Mismatch repair deficiency status, such as frequent PIK3CA mutation, was also seemed as a cause to carcinogenesis in colorectal cancer." (PMID 28424419, 2017). "We target common point mutations in the BRAF, KRAS and PIK3CA oncogenes in archival colorectal cancer samples to precisely map the spatial and morphological context of mutant subclones." (PMID 29222441, 2017). "The PIK3CA c.3140A>G (p.H1047R) and c.1633G>A (p.E545K) somatic mutations are commonly found in colorectal carcinoma, and were present in the colon cancer cells (HCT15 and HCT116, respectively) included in the published studies." (PMID 29152088, 2017). "In one case, we identified a PIK3CA D350G mutation, which has been identified in human breast, endometrial, pancreatic, and colorectal carcinomas." (PMID 29190660, 2017). "Such integrative research demonstrated potential benefits of aspirin in colorectal carcinoma with PIK3CA mutations, providing the basis for new clinical trials." (PMID 29552640, 2017). "PIK3CA mutations are observed in approximately 15% to 20% of human colorectal carcinomas, and are associated with proximal tumor location and KRAS mutations." (PMID 29152088, 2017). "We found that mutations in PIK3CA recurrently occurred as progressor mutations, suggesting that PIK3CA mutations are a late event in the evolution of colorectal cancer." (PMID 26890883, 2016). "Other studies confirmed the benefit of aspirin treatment on overall survival in PIK3CA mutated colorectal cancer." (PMID 27835884, 2016). "In contrast, both urothelial and colorectal cancers were reported to bear PIK3CA mutations with a probability of 15-20%." (PMID 27283768, 2016). "Aberrant activation of the inositide signaling pathway by a loss of function PTEN mutation or gain of function mutation/amplification of PIK3CA is an oncogenic mechanism in gastric cancer and colorectal cancer." (PMID 27242542, 2016). "Previous study demonstrates that aspirin has beneficial effect on colorectal cancer patients specifically harboring a mutated PIK3CA." (PMID 26918349, 2016). "Here, the authors show that oncogenic PIK3CA mutations drive this metabolic rewiring in colorectal cancer cells by up-regulating glutamate pyruvate transaminase expression, thus increasing sensitivity to glutamine starvation." (PMID 27321283, 2016). "Here we show that PIK3CA mutations reprogram glutamine metabolism by upregulating glutamate pyruvate transaminase 2 (GPT2) in colorectal cancer (CRC) cells, making them more dependent on glutamine." (PMID 27321283, 2016). "Here, we conducted a case-control study to investigate the association of a miR-520a binding site polymorphism rs141178472 in the PIK3CA 3′-UTR with the risk of colorectal cancer in a Chinese population." (PMID 25834816, 2015). "Currently also mutations at exon 20 of PIK3CA, although rarely found in colorectal cancer patients (less than 5% in most studies) have been demonstrated to determine resistance to anti-EGFR monoclonal antibodies." (PMID 25943333, 2015). "In colorectal carcinoma, somatic PIK3CA mutation was recognized as a molecular biomarker that predicts response to aspirin therapy." (PMID 25617745, 2015). "Mutations in genes such as KRAS, NRAS, BRAF and PIK3CA have become an important part of colorectal carcinoma evaluation." (PMID 26691448, 2015). "PIK3CA mutations occur in approximately 15% of colorectal cancers and of these 8–9% have mutations in both PIK3CA and KRAS." (PMID 25401499, 2014).
colorectal cancer (continued). "Mutations in KRAS, BRAF and PIK3CA are the most common somatic alterations found in the colorectal cancer (CRC) patients from Western countries; but their prevalence and prognostic value have not been adequately assessed in Asian patients." (PMID 25367198, 2014). "The PI3 kinase pathway has been previously associated with colorectal cancer, where PIK3CA mutations occur in approximately 15% of colorectal tumors." (PMID 24943349, 2014). "The association of PIK3CA overexpression with lymph node metastasis has been identified in colorectal cancer, gastric cancer, ESCC, etc.." (PMID 25054828, 2014). "Mutations in the oncogenic PIK3CA gene are found in 10–20% of colorectal cancers (CRCs) and are associated with poor prognosis." (PMID 25501831, 2014). "Although PIK3CA mutations preferentially occur together with activating KRAS-BRAF mutations in colorectal carcinoma, PIK3CA mutations tend to occur as isolated events, such as those in mismatch repair deficiency in gastric carcinoma." (PMID 25003395, 2014). "To model PIK3CA-activating mutations in late stages of cancer, we took advantage of the isogenic conversion of a PIK3CA-wild-type tumor into a PIK3CA H1047R-mutated tumor using the highly metastatic colorectal cancer cell line SW48." (PMID 23986086, 2013). "Another previous study of a small cohort of colorectal cancer patients reported that PIK3CA mutation is predictive of poor survival." (PMID 23617638, 2013). "In conclusion, we developed a CSC model from a colorectal cancer patient-derived xenograft tumor and identified a PIK3CA (H1047R) mutation in the CSC population as a predictive biomarker to guide targeted therapy." (PMID 23826249, 2013). "The first study in colorectal cancer reported that PIK3CA mutations were significantly associated with poor survival." (PMID 23617638, 2013). "Overall, our results suggest that the PI3K/mTOR pathway inhibitor PF-04691502 has potent anti-proliferative activity in PIK3CA mutant CSCs, warranting further evaluation of the inhibitors in colorectal cancer patients carrying PIK3CA mutations." (PMID 23826249, 2013). "PIK3CA mutations are a promising target in colorectal cancer, among others; now we need to optimize the administration of our therapies and identify the patient populations most likely to benefit." (PMID 23593290, 2013). "Colorectal cancer patients harboring the activating somatic PIK3CA mutation have the worst clinical outcomes." (PMID 23826249, 2013). "Mutations in the gene coding for the p110 α subunit, PIK3CA, have been detected in up to 32% of colorectal cancers analyzed." (PMID 24276379, 2013). "The PIK3CA gene codes for the catalytic subunit p110α of PI3Ks and is frequently mutated in various human cancers including colorectal cancer with a frequency of ∼30%." (PMID 23826249, 2013). "TRAIL sensitivity was not related to the presence of activating oncogenic KRAS, BRAF and PIK3CA mutations common to colorectal cancer." (PMID 23852390, 2013). "For colorectal carcinoma, the prevalence of PIK3CA mutation was reported to be between 7% and 32%, with G>A transversions in exon 9 being the most commonly observed configuration." (PMID 23785428, 2013). "PIK3CA mutation (overall, exon 9 and exon 20 hot spots) and other molecular characteristics of 757 colorectal carcinomas." (PMID 23785428, 2013). "We aimed to examine how PIK3CA mutations relate to other molecular alterations in colorectal carcinoma, to pathologic phenotype and survival." (PMID 23785428, 2013). "Summary of results from reported studies on PIK3CA mutation in colorectal carcinoma and various associations with molecular and pathological characteristics." (PMID 23785428, 2013). "PIK3CA mutation in 757 colorectal carcinomas (overall, exon 9 and exon 20 hot spots) and clinico-pathologic features." (PMID 23785428, 2013).